FPR2 (formyl peptide receptor 2)
Diseases named in the same sentence as FPR2 in open-access papers (continued):
Sharing a sentence is not in itself a finding about the gene and the disease.
Arthritis (12 papers, 2016 to 2025). Inflammation of a joint. "It has been shown that FPR2 ligation inhibits the expansion of effector pathogenic CD4+ T cells in two arthritis models, whereby FPR2 signaling enhances IL17 production in CD4+ T cells, while leaving IFNγ unchanged." (PMID 39148732, 2024). "FPR2 KO mice exhibit the impaired macrophage chemotaxis, abnormal neutrophil physiology, increased susceptibility to inflammatory disease (such as arthritis) and bacterial infection." (PMID 35797341, 2022). "Mice deficient in FPR2/3, the homologous to human FPR2, was used as a key model to address the role of FPR2 in the pathogenesis of arthritis." (PMID 34220836, 2021). "Only a selective FPR2 agonist alleviated arthritis symptoms, and positively impacted paw swelling and weight loss." (PMID 40181186, 2025). "For example, the stable epimer 17R-RvD1 and the ALX/FPR2 mimetic BML-111 significantly decrease arthritis severity and shorten the remission interval in murine inflammatory arthritis." (PMID 39125448, 2024). "The protective role of nEVs through AnxA1 binding with the formyl peptide receptor 2 (FPR2/ALX) present on chondrocytes was confirmed in vivo after the intra-articular injection of AnxA1-positive nEVs in a mouse model of K/BxN arthritis." (PMID 36291183, 2022). "Taken together, these studies reveal promise for FPR2‐targeted therapies as a potential treatment for arthritis, cardiovascular disease and renal disease." (PMID 35797341, 2022). "The functional role of FPR2 in the regulation of RA pathogenesis was also demonstrated by showing that deletion of annexin A1, an endogenous FPR2 agonist, exacerbates arthritis severity in K/BxN serum‐injected mice." (PMID 34378309, 2021). "Previously, treatment of cpd43 (a dual agonist of FPR1 and FPR2) has been reported to decrease clinical severity in the K/BxN serum-transfer arthritis model." (PMID 30279454, 2018). "Deletion of annexin A1 (an endogenous FPR2 agonist) has been shown to exacerbate arthritis severity in the K/BxN serum-injected mice, suggesting a crucial role of annexin A1 in the regulation of RA pathogenesis." (PMID 30279454, 2018). "Delivery of the anti-inflammatory signal through Fpr2 was also supported by the experiment where Fpr2−/− mice exhibited a striking exacerbation and prolongation of K/B × N serum transfer arthritis." (PMID 28809781, 2017). "FPR2-/- mice displayed an exacerbation of arthritis symptoms following K/BxN serum transfer, supporting the evidence that, in particular, FPR2 could mediate anti-inflammatory effects that could control RA pathogenesis." (PMID 34220836, 2021). "Here, we showed that a novel FPR2 agonist (scolopendrasin IX) elicited strong therapeutic effects against the K/BxN serum-transfer arthritis model, which was blocked by an FPR2 antagonist (WRW4), suggesting that stimulation of FPR2 resulted in therapeutic activity against RA." (PMID 30279454, 2018). "Notably, activation of FPR2 and the homologue receptor FPR1 has shown therapeutic benefit against disease symptoms in K/BxN serum transfer-induced arthritis (STIA)." (PMID 40181186, 2025). "In the absence of Fpr2/3, 17R-RvD1 no longer attenuated the clinical score, the swelling of hind paws, or the arthritis-related manifestation of cachexia, and disease penetrance was almost identical between the 2 genotypes (data not shown)." (PMID 27158677, 2016). "Data mining of published databases allowed the identification of increased FPR2 gene expression in RA PBMC: one could speculate the body itself might try to trigger necessary resolution responses when exaggerated inflammation is sensed, like during active arthritis." (PMID 40181186, 2025).
lung carcinoma (12 papers, 2015 to 2025). "In a metabolomic analysis we observed a significant increase in AA concentration in FPR2-stimulated lung cancer cell line CaLu-6." (PMID 38397818, 2024). "We further evaluated the effect of FPR2 stimulation on glucose metabolism in lung cancer CaLu-6 cells by using Seahorse XF glycolytic rate assay." (PMID 37875162, 2023). "By using a metabolomic approach, we have analysed metabolic pathways activated in FPR2-stimulated CaLu-6 cells, a human lung cancer cell line." (PMID 37875162, 2023). "These contradictory conclusions on FPR2 and WKYMVm in lung cancer and colon cancer need further verification." (PMID 36120322, 2022). "FPR2 inhibition significantly prevents cell proliferation and the malignant phenotype, suggesting the potential role of FPR2 signalling and, in turn, of phosphorylated proteins as drug targets in lung cancer epithelial cells." (PMID 31784636, 2019). "However, further studies in models of lung cancer should be performed in order to extend the knowledge on the role of FPR2 in metabolic reprogramming." (PMID 37875162, 2023). "Similar results were obtained in A549 lung cancer cell line expressing FPR2." (PMID 37875162, 2023). "Upregulated FPR2 suppresses epithelial-mesenchymal transition of lung cancer cells." (PMID 36033829, 2022). "In lung cancer, Fpr2 can inhibit tumor growth in mice subcutaneously transplanted with Lewis lung cancer (LLC) cells by limiting the macrophage response to the tumor-derived chemokine C-C motif chemokine ligand 2 (CCL2) and inhibiting the polarization of macrophage M2." (PMID 36120322, 2022).
colon cancer (10 papers, 2010 to 2024). "Moreover, experimental evidence suggests that FPR2 is associated with different cancer types, such as colon cancer, melanoma and ovarian cancer." (PMID 34439361, 2021). "The distribution of the formyl peptide receptor is not limited to phagocytosis of leukocytes but is also expressed in tumor cells such as colon cancer, which enhances drug resistance, and knockdown of FPR2 reduces the tumorigenicity of colon cancer." (PMID 39881881, 2024). "The expression of FPR1 in GC tissues is higher than that in normal tissues, which is closely related to the survival time of patients 50, and FPR2 is also highly expressed in endometrial and colon cancer." (PMID 38817876, 2024). "FPR2 overexpression has been reported in different pathologies, such as ovarian cancer, melanoma and colon cancer." (PMID 37627089, 2023). "FPR2 is highly expressed in human colon cancer cell lines, as well as in advanced colon cancer patients." (PMID 36120322, 2022). "The expression of FPR1 in gastric cancer tissue is higher than that in normal tissue and is closely related to the survival time of the patient, and FPR2 is also highly expressed in endometrial cancer and colon cancer." (PMID 33679387, 2020). "FPR2 promotes cancer progression in several cell lines and knocking down of FPR2 from colon cancer cell lines reduces their tumorigenicity." (PMID 32471307, 2020). "There were 10 high FPR2 expressing cases (89%) from colon cancer patients, but just 1 (11%) from rectal cancer patient." (PMID 28724995, 2017). "Taken together, these results suggested a close correlation between FPR1 expression and colorectal cancers while FPR2 expression might be more sensitive in the colon cancer and affects the invasive phenotype of human colon cancer more specifically." (PMID 28724995, 2017). "FPR2 promotes proliferation, EMT, angiogenesis and anti-apoptosis of colon cancer cells, and accelerates colon cancer progression." (PMID 36120322, 2022).
ovarian carcinoma (10 papers, 2013 to 2023). A malignant neoplasm originating from the surface ovarian epithelium. "Further studies revealed that secretion of Th2 cytokines was increased by ovarian cancer cells with high FPR2 expression, which induced M2-like macrophage polarization, and C3 transferase partly inhibited the polarization of M2 macrophages." (PMID 34930387, 2021). "In this study, we first demonstrated the interactions between FPR2 and RhoA in epithelial ovarian cancer cells." (PMID 34930387, 2021). "In this study, we preliminarily clarified the positive correlation of FPR2 and RhoA in ovarian cancer cells, and a RhoA inhibitor reversed the migration ability of EOCs, which was promoted by ectopic expression of FPR2." (PMID 34930387, 2021). "Further study of the mechanisms of FPR2-regulated macrophage polarization and its role in ovarian cancer progression is needed." (PMID 34930387, 2021). "In our study, we found that FPR2 played an auxoaction on the secretion of IL-10 and IL-4 in ovarian cancer cells and the induction of M2 macrophage polarization." (PMID 34930387, 2021). "FPR2 stimulated M2 macrophage polarization and promoted invasion and metastasis of ovarian cancer cells through RhoA." (PMID 34930387, 2021). "In a previous study, FPR2 was shown to be overexpressed in ovarian cancer tissues and to be located on the cell membrane by IHC." (PMID 34930387, 2021). "LL-37-stimulated genes are attenuated by the inhibition of FPR2, suggesting that LL-37 potentiates a more aggressive behavior from ovarian cancer cells through its interaction with this receptor." (PMID 23549262, 2013). "Likewise, most of the available data have evidenced a role for FPR2 as a marker of poor prognosis in cancer, particularly gastric cancer and also epithelial ovarian cancer." (PMID 35146757, 2022). "Here, we investigated whether RhoA is involved in the role of FPR2 in ovarian cancer invasion and migration." (PMID 34930387, 2021). "Therefore, we suggest that FPR2 stimulates M2 macrophage polarization and promotes invasion and metastasis of ovarian cancer cells through RhoA." (PMID 34930387, 2021). "Additionally, knocking down FPR2 inhibited the invasion and migration of ovarian cancer cells, potentially indicating that FPR2 plays a key role in cancer cell metastasis." (PMID 34930387, 2021). "The results showed that the tumour volumes and weights were significantly decreased after FPR2 knockdown, which suggested that FPR2 may play a role in ovarian cancer tumourigenesis (Fig. 7A1,A2,B and C)." (PMID 34930387, 2021). "In our previous study, we found that formyl peptide receptor 2 (FPR2) promoted the invasion and metastasis of epithelial ovarian cancer (EOC) and could be a prognostic marker for EOC." (PMID 34930387, 2021). "Thus, we suggest that FPR2 stimulates M2 macrophage polarization and promotes invasion and metastasis of ovarian cancer cells through RhoA." (PMID 34930387, 2021). "Moreover, FPR2 is closely related to the clinical prognosis of ovarian cancer patients." (PMID 34930387, 2021). "LL-37 induces invasion in ovarian cancer cells and stimulates MAPK and JAK/STAT signaling cascades, as well as the significant activation of several transcription factors, through both FPR2-dependent and FPR2-independent pathways." (PMID 23549262, 2013). "FPR2 can stimulate epithelial ovarian cancer (EOC) to secrete Th2 cytokines through ras homolog family member A (RhoA), increase the polarization of M2 macrophages, and promote the invasion and metastasis of ovarian cancer cells." (PMID 36120322, 2022). "Unlike MrgX2, FPRL1 (also known as FPR2), a member of the chemokine GPCRs, is expressed in a variety of cells including mast cells, neutrophils, macrophages and ovarian cancer cells." (PMID 26378047, 2015). "This is in contrast to the suggested role of ANXA1 in this form of ovarian cancer, suggesting the signalling of ANXA1 in this process may not be predominantly mediated through FPR2." (PMID 35146757, 2022).
Stroke (10 papers, 2019 to 2025). Sudden impairment of blood flow to a part of the brain due to occlusion or rupture of an artery to the brain. "FPR2 has also been described to play a protective and repairing role in ischemic heart disease and stroke." (PMID 33256815, 2020). "These experiments showed that selective antagonism of neutrophil Fpr2/ALX prevented the ability of AnxA1 to reduce PNA recruitment to the cerebral endothelium after stroke." (PMID 31154815, 2019). "Resolvin D1 is an endogenous ligand of FPR2, and its interactions reduce inflammation in stroke." (PMID 34650406, 2021). "FPR2 resolves inflammation by promoting non-phlogistic apoptosis, leukocyte phagocytosis, cell adhesion molecule shedding, and releasing anti-inflammatory cytokines in the tissues, thus being involved in ameliorating inflammatory storms in the early stages of reperfusion following stroke." (PMID 34650406, 2021). "In dataset GSE16561, with the threshold of p < 0.05, CLEC4D, GPR97, MCEMP1, and TSPAN14 were significantly upregulated in the stroke group (The platform GPL6883 did not explore FPR2's expression)." (PMID 35075378, 2022).
gastric cancer (9 papers, 2017 to 2025). A primary or metastatic malignant neoplasm involving the stomach. "FPR2 has been identified to promote the invasion and metastasis in various tumors including colorectal cancer and gastric cancer, and serves as a prognosticator in gastric cancer." (PMID 35675043, 2022). "FPR2, one of the famous receptors, has been reported to be involved in many kinds of carcinoma, including gastric cancer and colorectal cancer." (PMID 33816236, 2021). "A recent study has reported that the levels of FPR2 expression is directly correlated increased proliferation and invasion during gastric cancer (GC) progression and with the patients’ overall survival." (PMID 32290034, 2020). "In conclusion, we demonstrated that, for the first time, high expression of FPR2 in gastric cancer tissues is correlated with poor prognosis of GC patients." (PMID 28600569, 2017). "However, it is worth mentioning that the high FPR2 expression in gastric cancer might be a symptom of an underlying mechanism, which should be a target of therapeutic approaches besides FPR2 itself and its signaling pathway and needs to be further investigated." (PMID 28600569, 2017). "We also elucidated that FPR2 can enhance the invasion and metastasis of gastric cancer." (PMID 28600569, 2017). "For example, FPR1 exerts a tumor suppressor function in gastric cancer (GC) by inhibiting angiogenesis, while FPR2 has been reported to contribute to tumor progression by promoting invasion and metastasis of GC cells." (PMID 36120322, 2022). "For these reasons, our results suggest that FPR2, CARD14, CXCR2, EFNA2, CXCR1, AQP9 TRIP13, along with GHRL and KLK11, could be used as promising biomarkers for gastric cancer diagnosis or prognostic evaluation." (PMID 34012923, 2021). "Formyl peptide receptor 2 (FPR2), a classical chemoattractant receptor of G-protein-coupled receptors, is reported to be involved in invasion and metastasis of some cancers, but the role of FPR2 in gastric cancer (GC) has not yet been elucidated." (PMID 28600569, 2017).
COVID-19 (8 papers, 2020 to 2025). A disease caused by infection with severe acute respiratory syndrome coronavirus 2. "By activating ALX/FPR2 and ChemR23 receptors, resolvins modulate glia–neuron crosstalk and reduce neuronal hyperexcitability, providing neuroprotective effects in post-viral neuropathy and COVID-19–associated neuroinflammation." (PMID 41373540, 2025). "Future studies should evaluate whether hyperinflammation in COVID-19 patients can be diminished by targeting FPR2 through the administration of human recombinant AnxA1 or Ac2-26 peptide." (PMID 36556102, 2022). "While macrophages in COVID-19 samples expressed chemokines that primarily engage CC and CXC family chemokine receptors on neutrophils (orange box), macrophages in influenza samples expressed ligands that engage formyl peptide receptors (FPR), FPR1 and FPR2 (pink box)." (PMID 34618691, 2021).
meningitis (8 papers, 2011 to 2024). A disorder characterized by acute inflammation of the meninges of the brain and/or spinal cord. "FPR1 and FPR2 are crucial for bacterial immune defense, as FPR1- and FPR2-deficient mice are characterized by increased susceptibility to Listeria monocytogenes infection and meningitis caused by Streptococcus pneumoniae, in comparison to wild-type mice." (PMID 37512874, 2023). "Fpr2 deficiency aggravated meningitis resulting from severe S. suis infection." (PMID 33318141, 2021). "Fpr2 deficiency aggravates the host response to S. suis meningitis." (PMID 33318141, 2021). "Recent studies have shown that, apart from anti-viral immunity and pathogen clearance functions, annexin 1 attenuates neutrophil migration and IL-6 expression through formyl peptide receptor 2 in a Streptococcus suis induced meningitis mouse model." (PMID 38907250, 2024). "We also elucidated the function of Fpr2 at different infection sites by comparing the STSLS model with the S. suis-meningitis model." (PMID 36776849, 2023). "AnxA1 attenuated inflammatory responses and neutrophil invasion through Fpr2 during S. suis meningitis." (PMID 36776849, 2023). "Injection of dexamethasone decreased the mortality of Fpr2-/- mice in the meningitis model, but accelerated the death in Fpr2-/- mice with STSLS." (PMID 36776849, 2023). "AnxA1 conferred protection against inflammatory responses and neutrophil invasion during S. suis-induced meningitis mainly through Fpr2." (PMID 33318141, 2021). "AnxA1 attenuates inflammatory responses and brain damage through Fpr2 in mice with S. suis infection meningitis." (PMID 33318141, 2021). "Together, these data demonstrated that AnxA1 suppresses neutrophil invasion and promotes bacterial removal in the brains of mice with S. suis-induced meningitis through Fpr2." (PMID 33318141, 2021). "In this study, we used Fpr2−/− mice to estimate the role of murine Fpr2 and exogenous AnxA1 in S. suis-induced meningitis." (PMID 33318141, 2021). "With a particular emphasis on the function of AnxA1 in the regulation of neutrophil recruitment and interleukin-6 (IL-6) production in S. suis-induced meningitis, we demonstrate an immunomodulatory role for AnxA1 in S. suis-induced infection through Fpr2." (PMID 33318141, 2021). "AnxA1 reduces neutrophil invasion and bacterial loads through Fpr2 in mice with S. suis meningitis." (PMID 33318141, 2021). "Future studies are needed to address whether neutrophil phagocytosis by astrocytes or microglia occurs during S. suis meningitis and whether such a potentially protective effect is mediated by Fpr2." (PMID 33318141, 2021). "Ac2-26 and other FPR2 modulators might be promising targets for the development of novel therapies for Streptococcus pneumoniae-induced meningitis." (PMID 33121515, 2020). "Finally, we were interested whether the meningitis-induced astrocyte and microglia response are ameliorated in Ac2-26-treated Fpr1−/− and Fpr2−/− mice." (PMID 33121515, 2020). "By comparing the S. suis-meningitis model to the STSLS models, we were able to identify differences in the immune regulation mechanism of Fpr2 in these different S. suis infection models." (PMID 36776849, 2023). "In this study, we uncovered that the lack of Fpr2 exacerbated S. suis-induced meningitis in mice infected with the Chinese virulent strain 05ZYH33, and AnxA1 administration exerted anti-inflammatory effects through Fpr2 in S. suis-infected mice." (PMID 33318141, 2021). "We also found that AnxA1 decreased neutrophil adhesion through Fpr2, and AnxA1 decreased IL-6 expression through the Fpr2/p38/COX-2 pathway, which may clarify the mechanism by which the protein decreased cytokine expression and brain damage during S. suis meningitis." (PMID 33318141, 2021).
colorectal cancer (7 papers, 2017 to 2025). A primary or metastatic malignant neoplasm that affects the colon or rectum. "High expression of FPR2 has been implicated in modulating tumor-associated inflammation and promoting tumor cell migration and invasion, such as gastric and colorectal cancer." (PMID 41376620, 2025).
glioblastoma (7 papers, 2020 to 2025). The most malignant astrocytic tumor (WHO grade IV). "For instance, FPR2 may promote the malignancy of human colon cancer, while FPR1 is linked to the progression of human glioblastoma multiforme (GBM)." (PMID 32038501, 2020).